ARG2 (arginase 2)
Diseases named in the same sentence as ARG2 in open-access papers (continued):
Sharing a sentence is not in itself a finding about the gene and the disease.
prostate carcinoma (8 papers, 2010 to 2024). A carcinoma that arises from epithelial cells of the prostate gland. "ARG2 expression is also androgen regulated and has been linked to immunosuppressive pathways in human prostate cancer." (PMID 29464091, 2018). "We identified two genes, CD38 and ARG2 that appear to be associated with prostate cancer differentiation." (PMID 29464091, 2018). "The finding that the percentage of ARG2 staining was prognostic in the Stanford-TMA cohort suggests that ARG2 expression could be a marker of differentiation and that its loss correlates with more aggressive prostate cancer." (PMID 29464091, 2018). "Our data clearly demonstrate that CD38 and ARG2 identify three different differentiation states in prostate cancer." (PMID 29464091, 2018). "A detailed investigation of the gene expression relationship between CD38 and ARG2 demonstrated Boolean relationship “CD38 high => ARG2 high” and three possible groupings of prostate cancer cases: CD38+ARG2+, CD38-ARG2+, and CD38-ARG2-." (PMID 29464091, 2018). "Using gene expression data, we identified two markers, CD38 and ARG2, that group prostate cancer into three differentiation states." (PMID 29464091, 2018). "It has been reported that ARG2 is aberrantly expressed in prostate cancer cells, being involved in tumor immune escape mediated by arginine consumption, resulting in a lack of arginine that weakens tumor-infiltrating lymphocytes and renders them dysfunctional." (PMID 23424623, 2013). "Previous studies have shown the expression of ARG2 in prostate cancer cell lines and its functional role in prostate cancer development." (PMID 21347291, 2011). "ARG2 is known to be involved in polyamine metabolism and polyamines such as ornithine, spermine and spermidine play a critical role in prostate cancer development." (PMID 21347291, 2011). "In both our DASL data and TCGA RNAseq data, there was significantly higher expression of ARG2 in tumor samples in the young than the older cohort, which may suggest a stronger oncogenic role of ARG2 in the development of prostate cancer in young men." (PMID 28027300, 2016). "In contrast to prostate cancer, ARG2 expression was rarely demonstrated in PDC cells by immunohistochemistry, and instead ARG2 was characteristically expressed in α-smooth muscle actin-positive cancer-associated fibroblasts (CAFs), especially those located within and around necrotic areas in PDC." (PMID 23424623, 2013). "It has been reported that arginase II (ARG2), one of two ARGs, is aberrantly expressed in prostate cancer cells, which convert arginine into ornithine, resulting in a lack of arginine that weakens tumor-infiltrating lymphocytes and renders them dysfunctional." (PMID 23424623, 2013). "In conclusion, the current study identified potential novel biomarkers for prostate cancer development and/or progression such as eIF4A3, DDAH1, ARG2, Prdx3, and Prdx4 from proteomic data using systems biology approach." (PMID 21347291, 2011). "High levels of ARG2 and reduced levels of NO and iNOS were observed in prostate cancer cells, compared to non-cancerous tissues." (PMID 39337272, 2024). "ARG2 expression has been reported to be relatively higher in normal and non-malignant prostatic tissues compared to prostate cancer tissues." (PMID 29464091, 2018). "Protein network analysis and clustering of differentially expressed proteins revealed new targets such as DDAH1, ARG2, EIF4A3, Par4, PPA2, Prdx3 and Prdx4, which need further validation to define their potential application in clinical relevance in prostate cancer." (PMID 21347291, 2011).
Hepatic steatosis (7 papers, 2016 to 2025). Steatosis is a term used to denote lipid accumulation within hepatocytes. "ARG-2 deficiency leads to spontaneous development of hepatic steatosis and proinflammatory activation." (PMID 35492579, 2022). "Hepatocyte-specific Arg2 overexpression enhances basal thermogenesis, and protects from weight gain, insulin resistance, glucose intolerance, hepatic steatosis and hepatic inflammation in diabetic mouse models." (PMID 30962478, 2019). "Hepatic Arg2 overexpression protected mice from diet- and genetically-induced insulin resistance, adiposity and hepatic steatosis and inflammation." (PMID 30962478, 2019). "We examined the role of Arg2 in mediating the major hallmarks of hepatic steatosis and inflammation." (PMID 30962478, 2019). "Mechanistically, MCT4 alleviated hepatic steatosis by regulating a group of hub genes such as Arg2, Olr1, Cd74, Mmp8, Irf7, Spp1, and Apoe, which in turn impacted multiple pathways involved in lipid metabolism and inflammatory response, such as PPAR, HIF-1, TNF, IL-17, PI3K-AKT, Wnt, and JAK-STAT." (PMID 40330148, 2025). "We next examined the hypothesis that genetic reconstitution of hepatic RGS16 in the context of Arg2 overexpression would reverse the improvements in hepatic steatosis, inflammation and insulin and glucose intolerance observed in Arg2-treated db/db mice." (PMID 30962478, 2019). "Furthermore, Arg2 overexpression per se attenuates insulin resistance, hepatic steatosis and inflammation in high-fructose-fed and genetically obese models." (PMID 30962478, 2019). "We show that Arg2 attenuates hepatic steatosis, independent of mitochondrial localization or ureahydrolase activity, and that enzymatic arginase activity is dispensable for Arg2 to augment total body energy expenditure." (PMID 38280549, 2024). "Arg2 exerts important physiological function (eg, increased heat generation, blockade of hepatic steatosis) independent of its enzymatic competency." (PMID 38280549, 2024).
Insulin resistance (6 papers, 2019 to 2025). Increased resistance towards insulin, that is, diminished effectiveness of insulin in reducing blood glucose levels. "In obese mouse models, linarin effectively ameliorates insulin resistance and inflammatory responses through modulation of the c-FOS/ARG2 signaling axis." (PMID 40736877, 2025). "Clinically, this Arg2-regulated bypass route may be exploited to treat NAFLD and insulin resistance." (PMID 30962478, 2019).
lung carcinoma (6 papers, 2013 to 2025). "Lung cancer expresses ARG2, although immune suppression mediated by ARG2-expressing cancer cells has not been observed." (PMID 23424623, 2013). "High levels of endogenous arginase 2 (ARG2) have been previously reported in human lung cancers." (PMID 30808864, 2019). "In contrast, ARG2 function was shown to be not critical in lung cancer in a prior study." (PMID 30728077, 2019). "However, immune suppression mediated by ARG2-expressing cancer cells in lung cancer has not been observed." (PMID 23424623, 2013).
type 2 diabetes (6 papers, 2018 to 2025). "In the next paragraph, we will describe how ARG2 in islet beta cells could be implicated in the pathogenesis of type 2 diabetes." (PMID 34829980, 2021). "Here, we discuss several features of ARG2 and polyamines, which can be relevant to the pathophysiology of type 2 diabetes." (PMID 34829980, 2021). "In human pancreatic beta cells, ARG2 is downregulated in type 2 diabetes." (PMID 34829980, 2021). "In this review, we focus on the presence and possible role of ARG2 and polyamines in human pancreatic beta cells, which may be relevant to the pathophysiology of type 2 diabetes (T2D)." (PMID 34829980, 2021). "Analysis of islet alpha and beta cell-enriched fractions from five non-diabetic and four type 2 diabetic OD by RT-qPCR showed that ARG2, PPP1R1A and TMEM37 were enriched in beta cells and downregulated in type 2 diabetes." (PMID 29185012, 2018).
acute myeloid leukemia (5 papers, 2021 to 2024). Acute myeloid leukemia (AML) is a group of neoplasms arising from precursor cells committed to the myeloid cell-line differentiation. "A similar mechanism is exploited by acute myeloid leukemia (AML) primary blasts, which have an increased expression and activity of ARG2, thus favoring an immunosuppressive microenvironment." (PMID 34277645, 2021).
leukemia (5 papers, 2018 to 2022). A malignant (clonal) hematologic disorder, involving hematopoietic stem cells and characterized by the presence of primitive or atypical myeloid or lymphoid cells in the bone marrow and the blood. "In vivo antitumor activity was determined in syngeneic models of colorectal and kidney carcinomas (CT26 and Renca, respectively), as well as in an ARG2-dependent xenograft model of leukaemia (K562)." (PMID 36010962, 2022). "Together, we conclude that both HIF1–α and HIF2–α contribute to the hypoxic induction of ARG2 in leukemia cells." (PMID 30307989, 2018). "Six genes were identified in baboons (WNT3, POU2AF1, CCR7, ARG2, CD177, and WLS) and validated in human leukemia patients exposed to radiotherapy." (PMID 33737626, 2021). "While nor−NOHA itself is promising in targeting the leukemia hypoxic response, we unexpectedly found that its anti-leukemic activity was independent of ARG2 inhibition." (PMID 30307989, 2018). "Since nor−NOHA is effective in targeting ARG2-expressing leukemia cells, we wondered if nor−NOHA could attenuate hypoxia−mediated imatinib resistance in CML cells." (PMID 30307989, 2018).
colitis (4 papers, 2020 to 2025). Inflammation of the colon. "That meant the expression patterns of Arg2 and Cyp2e1 exhibit high coordination, indicating an intense regulation between them, in the condition of experimental colitis and 2′‐FL administration." (PMID 40501496, 2025). "The expression of Arg2 can be upregulated in response to intestinal oxidative stress in mice with DSS‐induced colitis and patients with ulcerative colitis." (PMID 40501496, 2025). "This was consistent with and explained the synchronized upregulation of Arg2 and Cyp2e1 in DSS‐induced colitis in the present study." (PMID 40501496, 2025). "In the present study, Arg2 and Cyp2e1 were significantly increased in DSS‐induced colitis mice and decreased by 2′‐FL." (PMID 40501496, 2025). "Several genes such as Gata3, Itk, Ccl8, Ccl22, Ccr4, Crlf2, Il9r, Il1rl1, and Arg2 are regulated concordantly in T-cell transfer colitis, acute DSS colitis and the time point representing high inflammation in the DSS time course." (PMID 34136502, 2021). "Increased ARG2 and DHFR seem to aggravate colitis by altering mucosal immunity." (PMID 34887863, 2021).
gastritis (4 papers, 2011 to 2021). Inflammation of the stomach. "The balance of the expression of NOS2 and arginase defines iNOS-dependent microbicidal capacity in an inflammatory environment; the deletion of arginase 2 (ARG2) in an experimental model results in increased gastritis and decreased bacterial load during H. pylori infection." (PMID 31320834, 2019). "We also previously found that mice lacking arginase 2 (Arg2) exhibit increased gastritis and lower colonization than wild type mice following infection with H. pylori." (PMID 22194986, 2011). "The analysis of the gene expression of ARG1, ARG2, and NOS2 was performed in the patients with chronic active gastritis, chronic inactive gastritis, no gastritis, or the control group." (PMID 31320834, 2019).
glioma (4 papers, 2017 to 2021). A benign or malignant brain and spinal cord tumor that arises from glial cells (astrocytes, oligodendrocytes, ependymal cells). "Using transcriptomic data from The Cancer Genome Atlas (TCGA), we examined ARG1 and ARG2 expression in human gliomas of different WHO grades II, III, IV." (PMID 34504786, 2021). "Exploring various public datasets we found the elevated expression of ARG1 and ARG2 in high grade gliomas, in particular in highly aggressive GBMs." (PMID 34504786, 2021). "Interrogation of single-cell sequencing data from gliomas shows ARG1 and ARG2 expression in both malignant cells and microglia/macrophages in human high grade gliomas." (PMID 34504786, 2021). "Overall, these results confirm high ARG1 and ARG2 expression in human malignant cells and glioma-infiltrating monocytes/macrophages." (PMID 34504786, 2021). "Augmented production of Trp and arginine, and elevated expression of metabolic enzymes IDO1, ASL and ARG2 in glioma cells were accompanied by increased infiltration of Tregs." (PMID 34211978, 2021). "In all tumour types studied, except glioma, ARG2 and OTC ranked gene lists significantly correlated with KRAS signaling." (PMID 28969007, 2017). "The elevated levels of other metabolic enzymes including argininosuccinate lyase (ASL), ARG2, and COX-2 in glioma cells led to augmented synthesis of Trp, arginine and PGE2, which induced the repression of CTLs as well." (PMID 34211978, 2021).
osteosarcoma (4 papers, 2017 to 2025). A usually aggressive malignant bone-forming mesenchymal neoplasm, predominantly affecting adolescents and young adults. "This has previously been shown in two ALT-positive osteosarcoma cell lines, and was thought to be due to elevated levels of ARG2." (PMID 39921567, 2025). "Hypoxia-induced ARG2 overexpression supports cell proliferation in osteosarcoma." (PMID 32121248, 2020). "MTOR signaling, a known downstream effector of amino acid metabolism and a target for novel agents in relapsed paediatric tumours, was enriched within osteosarcoma for both OTC and ARG2." (PMID 28969007, 2017). "In osteosarcoma, both ARG1 and ARG2 catabolic enzymes were moderately expressed." (PMID 28969007, 2017).
pulmonary hypertension (4 papers, 2018 to 2024). Increased pressure within the pulmonary circulation due to lung or heart disorder. "We found four genes to be significantly associated with high-altitude pulmonary hypertension (i.e., estimated mPAP ≥ 30 mm Hg) after adjustment for multiple testing: NOS3 rs2070744 (p = 0.003), ARG2 rs3742879 (p = 0.003), DDAH1 rs233122 (p = 0.004), and AGXT2 rs37369 (p = 0.003)." (PMID 34945057, 2021). "Therefore, we selected 16 single nucleotide polymorphisms in NOS3, DDAH1, DDAH2, AGXT2, ARG1, ARG2, and PRMT1 genes and studied their associations with dimethylarginine concentrations and the incidence of high-altitude pulmonary hypertension as well as acclimatization to high altitude." (PMID 34945057, 2021).
acute kidney injury (3 papers, 2023 to 2025). Sudden and sustained deterioration of the kidney function characterized by decreased glomerular filtration rate, increased serum creatinine or oliguria. "Noteworthily, in the kidney, ARG2 upregulation has been associated with ischemia–reperfusion-induced acute kidney injury and the identification of a specific inhibitor was suggested." (PMID 37834229, 2023).
fibrosis (3 papers, 2010 to 2020). the formation of excess fibrous connective tissue in an organ or tissue in a reparative or reactive process. "Toward this goal, we used several approaches such as arginase inhibition in conjunction with full-body Arg2-deficient mice and cell-specific Arg2 knockout in renal endothelial and proximal tubular cells in a well-established UUO fibrosis model." (PMID 32956070, 2020). "Sixth, coronary perivascular fibrosis in DOCA-salt mice is prevented or reduced by deletion of ARG1+/− or ARG2−/−, respectively." (PMID 23908657, 2013). "The major findings of this study are the contributions of arginase (ARG1 and ARG2) to elevated blood pressure, impaired EC-dependent vasorelaxation, increased vasoreactivity to constrictor stimuli, and enhancement of coronary perivascular fibrosis in a model of DOCA-salt hypertension." (PMID 23908657, 2013). "Although our findings confirmed that expression of arginase-2 contributes significantly to muscle fibrosis in mdx dystrophy, ablation of arginase-2 expression did not reduce mdx cardiac fibrosis." (PMID 20505827, 2010).
glioblastoma (3 papers, 2016 to 2023). The most malignant astrocytic tumor (WHO grade IV). "However, the role of ARG2 in the pathogenesis of glioblastoma (GBM) is unknown." (PMID 27363017, 2016). "However, the role of ARG2 in the pathogenesis of glioblastoma (GBM) and the HCMV effects on ARG2 are unknown." (PMID 27363017, 2016).
heart failure (3 papers, 2012 to 2025). Inability of the heart to pump blood at an adequate rate to meet tissue metabolic requirements. "Although literature reports a role for mitochondrial Arginase 2 (ARG2) in heart failure, contradictory results are reported." (PMID 41187268, 2025).
hepatocellular carcinoma (3 papers, 2024 to 2025). A malignant tumor that arises from hepatocytes. "HNF4A-AS1 suppressed hepatocellular carcinoma progression via enhancing PCBP2 degradation through ubiquitin and destabilizing ARG2 mRNA." (PMID 40641925, 2025).
injury (3 papers, 2016 to 2024). Damage inflicted on the body as the direct or indirect result of an external force, with or without disruption of structural continuity. "Our present in vivo results suggest the possibility that Gas6/Mer signaling-induced LXRα/Arg2 pathway during LPS-induced acute lung injury leads to downregulated NO production, which in part contributes to the resolution of acute lung injury." (PMID 27406916, 2016). "In the absence of Arg2 (Arg2–/– mice), there is an observed increase in microglial cell activation and pain behavior following nerve injury." (PMID 38419796, 2024). "Arg2-/- mice have lower plasma CREA and BUN levels after renal injury." (PMID 31057604, 2019).
ischemia (3 papers, 2016 to 2025). A hypoperfusion of the BLOOD through an organ or tissue caused by a PATHOLOGIC CONSTRICTION or obstruction of its BLOOD VESSELS, or an absence of BLOOD CIRCULATION. "While some studies linked ARG1 to the cardiac ischemia/reperfusion injury, others suggest a role of ARG2 in this context." (PMID 41187268, 2025).
metastatic melanoma (3 papers, 2022 to 2025). A melanoma that has spread from its primary site to another anatomic site. "Mechanistically, the expression of the mitochondrial enzyme arginase 2 (ARG2) was preferentially increased in Tregs in metastatic melanoma compared to other diseases, such as psoriasis." (PMID 34417572, 2022). "Compared to psoriatic Tregs, healthy Tregs express almost 4-fold more ARG-2; similarly, Tregs in metastatic melanoma lesions express high levels of ARG-2 protein, with these levels being higher in tumour-infiltrating Tregs than in Tregs isolated from healthy skin." (PMID 39861764, 2025). "Similarly, arginase 2 (ARG2) expression has been reported to suppress the proliferation of CD4+ effector T cells and facilitate Treg accumulation by inhibiting the mTOR signaling pathway in metastatic melanoma." (PMID 38791327, 2024).
metastatic tumor (3 papers, 2014 to 2022). "We also examined the expression of relevant N1- and N2-neutrophil markers in lung metastatic tumors by immunofluorescence analysis and found that EMCNecko mice could induce N2 neutrophils (Arg2+) to infiltrate metastatic tumors." (PMID 36184589, 2022). "ARG2 protein expression was identified in 50% of BCs and 63.6% of BCBMs whereas there was no detectable ARG2 expression in a small cohort of primary BCs that did not develop metastatic disease." (PMID 36423363, 2022).
nonalcoholic fatty liver disease (3 papers, 2019 to 2025). "In addition, recent studies have shown that deletion of arginase 2 ameliorates high-fat induced obesity and the associated nonalcoholic fatty liver disease (NAFLD)." (PMID 31842363, 2019).
pancreatic ductal carcinoma (3 papers, 2013 to 2025). "In pancreatic ductal carcinoma, there was an aberrant expression of the arginase 2 (ARG2) in hypoxic CAFs." (PMID 35884382, 2022). "Here we studied the expression of ARG2 in pancreatic ductal carcinoma (PDC) tissue clinicopathologically by examining over 200 cases of PDC." (PMID 23424623, 2013).
renal carcinoma (3 papers, 2019 to 2022). A carcinoma arising from the epithelium of the renal parenchyma or the renal pelvis. "Previous studies suggested arginase 2 expression and activity is important for breast and renal cancer cell growth in vitro by replenishing the intracellular polyamine pools and other mechanisms yet to be discovered." (PMID 30728077, 2019).